USP45 (ubiquitin specific peptidase 45)
Description:
Catalyzes the deubiquitination of SPDL1. Plays a role in the repair of UV-induced DNA damage via deubiquitination of ERCC1, promoting its recruitment to DNA damage sites. May be involved in the maintenance of photoreceptor function. May play a role in normal retinal development (By similarity). Plays a role in cell migration.
Synonyms: MGC14793; LCA19
Tractability: PROTAC: ubiquitination databases record sites on it.
Target class: Enzyme; Hydrolase
Gene: Protein-coding gene on chromosome 6 (99,432,325 to 99,521,728, reverse strand). Ensembl gene ENSG00000123552.
Subcellular location: Photoreceptor inner segment; Cytoplasm; Nucleus
Subcellular location (Human Protein Atlas): Cytosol; Nucleoplasm
Pathways (Reactome):
DNA Repair: Formation of Incision Complex in GG-NER
Gene Ontology:
Molecular function: cysteine-type deubiquitinase activity; protein binding; zinc ion binding
Biological process: cell migration; DNA repair; protein deubiquitination; global genome nucleotide-excision repair; neural retina development; photoreceptor cell maintenance
Cellular component: cytoplasm; cytosol; nucleoplasm; nucleus; photoreceptor inner segment
Genetic constraint (gnomAD): Loss-of-function variants: 53 observed, 61.12 expected, observed/expected ratio (o/e) 0.87, 90% interval 0.69 to 1.09. The upper end of that interval is the gene's LOEUF score, 1.09, which puts it in group 4 of 6, group 1 being the genes least tolerant of losing a copy. Missense variants: 720 observed, 773.36 expected, observed/expected ratio (o/e) 0.93, 90% interval 0.88 to 0.99. Synonymous variants: 221 observed, 261.73 expected, observed/expected ratio (o/e) 0.84, 90% interval 0.76 to 0.94.
Homologues: Orthologues: chimpanzee USP45 (99% identical), macaque USP45 (95% identical), pig USP45 (82% identical), rabbit USP45 (81% identical), mouse Usp45 (78% identical), rat Usp45 (77% identical), guinea pig USP45 (61% identical), tropical clawed frog usp45 (56% identical), zebrafish usp45 (52% identical), dog USP45 (29% identical). Paralogues in human: USP16 (38% identical), USP19 (18% identical), USP32 (17% identical), USP15 (17% identical), USP24 (17% identical), USP9X (17% identical), USP4 (16% identical), USP11 (16% identical), USP9Y (16% identical), USP2 (16% identical), USP22 (15% identical), USP31 (15% identical), and 59 more.
Diseases named in the same sentence as USP45 in open-access papers:
USP45 is named in the same sentence as 31 diseases in open-access papers, as found by Europe PMC text mining. Sharing a sentence is not in itself a finding about the gene and the disease. The quoted sentences say what the papers report.
cervical cancer (2 papers, 2023 to 2025). A primary or metastatic malignant neoplasm involving the cervix. "Interestingly, we first found that USP45 was highly expressed in cervical cancer tissues and associated with MYC signaling pathways." (PMID 36765885, 2023). "Further, we have discovered that increased USP45 expression significantly promoted cervical cancer cell proliferation, stemness and drug resistance, while USP45-enhanced MYC stability facilitated only stemness and drug resistance." (PMID 36765885, 2023). "On the basis of our investigations, we have discovered that USP45 as a new deubiquitinase of MYC significantly promoted cervical cancer development, stemness and drug resistance." (PMID 36765885, 2023). "The survival analysis from the “GEPIA2” database revealed that only cervical cancer patients with high USP45 expression exhibited poor overall survival (OS) and disease-free survival (DFS)." (PMID 36765885, 2023). "These bioinformatics analysis data revealed that USP45 might play a critical role in cervical cancer and activate MYC target signaling pathways." (PMID 36765885, 2023). "We established the cervical cancer SiHa cells stably expressing USP45 or C199A." (PMID 36765885, 2023). "Therefore, we explored the regulatory mechanism of USP45-MYC in cervical cancer." (PMID 36765885, 2023). "Further, we have discovered that USP45 was a novel deubiquitinating enzyme of MYC, and its overexpressing enhanced cervical cancer stemness and drug resistance." (PMID 36765885, 2023). "We demonstrated that USP45 inhibition via destabilizing MYC suppressed the stemness and drug resistance of cervical cancer cells." (PMID 36765885, 2023). "Furthermore, we have found that USP45 inhibition with a natural small molecule promoted MYC degradation and, in turn, reduced MYC-mediated stemness and drug resistance in cervical cancer." (PMID 36765885, 2023). "The “GSE63514” dataset showed that USP45 expression in the cancer tissues was elevated, but MYC was not significantly changed in cervical cancer tissues, compared with the normal tissues or stage CIN I-III." (PMID 36765885, 2023).
cervical tumors (1 paper, 2023). "Since USP45 is significantly expressed in cervical tumors, we have discovered that the combination of α-mangostin and doxorubicin can significantly inhibit USP45-induced cervical tumorigenesis in an animal model." (PMID 36765885, 2023).
colorectal adenocarcinoma (1 paper, 2022). The most common type of colorectal carcinoma. "The frequency of mutations in USP45 was higher in UCEC, colorectal adenocarcinoma (COADREAD), CESC, MESO, and SKCM, at 5.85%, 2.43%, 1.38%, 1.22%, and 1.07%, respectively." (PMID 35836933, 2022).
COVID-19 (1 paper, 2024). A disease caused by infection with severe acute respiratory syndrome coronavirus 2. "DAW1, ESF1, KCTD2, USP45, PNMA8A, SYNDIG1L, and CC2D2B are novel genes/proteins that may be linked to COVID-19." (PMID 38674024, 2024).
Fanconi anemia (1 paper, 2023). Fanconi anemia (FA) is a hereditary DNA repair disorder characterized by progressive pancytopenia with bone marrow failure, variable congenital malformations and predisposition to develop hematological or solid tumors. "The DUB proteins USP1, OTUB1, UCHL5, USP7, and PSMD14 were reported to contribute to double-strand break repair, USP1 to Fanconi anemia pathway, USP1 and USP7 to translesion repair, USP7 and USP47 to base excision repair, and USP7 and USP45 to nucleotide excision repair." (PMID 37892185, 2023).
melanoma (1 paper, 2025). A malignant, usually aggressive tumor composed of atypical, neoplastic melanocytes. "Collectively, these findings demonstrate that USP45 enhances the stability of MRGPRF in melanoma cells, likely by eliminating its K63‐linked ubiquitination." (PMID 40788071, 2025). "USP45 levels are negatively associated with higher T and N stages, although uncorrelated with M stages of melanoma." (PMID 40788071, 2025). "Bioinformatic analyses corroborate that USP45 mRNA levels are downregulated in melanoma, and low USP45 expression is associated with poor patient prognosis." (PMID 40788071, 2025). "To explore the role of USP45 in melanoma, we initially conducted IHC to compare USP45 protein levels between control skin and melanoma samples." (PMID 40788071, 2025). "Collectively, these observations demonstrate that USP45 acts as a suppressor of melanoma, possibly by stabilizing MRGPRF." (PMID 40788071, 2025). "Despite a lower expression of USP45 in melanoma cells compared to keratinocytes, our data reveal variation in USP45 expression across different melanoma cell lines." (PMID 40788071, 2025). "Survival analysis consistently demonstrated that melanoma patients with elevated USP45 expression exhibited a more favorable prognosis." (PMID 40788071, 2025). "Mechanistically, USP45's catalytic domain directly binds to the N‐terminal of MRGPRF and stabilizes MRGPRF, likely by removing its K63‐linked ubiquitination in melanoma cells." (PMID 40788071, 2025). "To assess the function of USP45 in melanoma cells, we overexpressed USP45 in A375 cells and knocked down USP45 in SK‐MEL‐2 cells, as A375 and SK‐MEL‐2 cells express the lowest and highest levels of USP45, respectively, among the melanoma cells we examined." (PMID 40788071, 2025). "We also examined USP45 mRNA and protein levels in the immortalized human keratinocyte cell line HaCaT and human melanoma cell lines A875, SK‐MEL‐28, A375, and SK‐MEL‐2." (PMID 40788071, 2025). "USP45 acts as a melanoma suppressor by stabilizing MRGPRF, which weakens the PI3K/AKT pathway, suppresses tumor growth, and reduces melanoma cell migration and invasion." (PMID 40788071, 2025). "It is noteworthy that the impact of overdosed USP45 on melanoma cells in vivo appears slightly milder than its effect observed in vitro." (PMID 40788071, 2025). "Our finding that USP45 functions as a melanoma suppressor contrasts with these oncogenic USPs, suggesting that the specific substrates targeted by USPs determine their roles in melanoma." (PMID 40788071, 2025). "Supporting these findings, our bioinformatic analysis using published transcriptomic datasets confirms that USP45 expression is significantly lower in melanoma tissues." (PMID 40788071, 2025). "qPCR and Western blot data findings clearly indicate that USP45 expression is reduced in these melanoma cell lines compared to HaCaT cells." (PMID 40788071, 2025). "We also assessed USP45 expression in melanoma and normal skin using published transcriptomic datasets and evaluated the relationship between USP45 expression and the prognosis of melanoma patients." (PMID 40788071, 2025). "In vivo, a melanoma xenograft mouse model shows that USP45 overexpression significantly impairs melanoma progression." (PMID 40788071, 2025). "To delineate the mechanism by which USP45 stabilizes MRGPRF in melanoma cells, we treated A375 and SK‐MEL‐2 cells with protein synthesis inhibitor CHX and proteasome inhibitor MG132." (PMID 40788071, 2025). "Comparing their expression levels and deciphering their functions in melanocytes would enhance our understanding of the USP45–MRGPRF axis in melanoma tumorigenesis." (PMID 40788071, 2025). "Functional assays demonstrate that USP45 overexpression inhibits melanoma cell malignancy, whereas USP45 knockdown promotes it." (PMID 40788071, 2025). "The results indicated that USP45 protein levels are lower in melanoma tissues compared to the epidermis of normal skin." (PMID 40788071, 2025).
melanoma (continued). "Finally, the impact of USP45–MRGPRF axis in other signaling pathways that are involved in melanoma progression, such as the RAS/MAPK pathway, remains to be determined." (PMID 40788071, 2025). "Furthermore, our xenograft assay only demonstrates that excessive USP45 inhibits proliferation and induces apoptosis of melanoma in vivo." (PMID 40788071, 2025). "This deeper understanding could provide valuable insights into the molecular mechanisms by which USP45 influences its substrates and modulates melanoma progression." (PMID 40788071, 2025). "To assess whether USP45 inhibits melanoma progression in vivo, we constructed USP45‐overexpressing stable A375 cells and injected them or control A375 cells into nude mice to establish xenograft models." (PMID 40788071, 2025). "Furthermore, we examined the role of USP45 in melanoma cell lines and a melanoma xenograft model." (PMID 40788071, 2025). "Additionally, USP45 expression in stage II–IV melanoma is lower than in stage I melanoma." (PMID 40788071, 2025). "Additionally, the USP45–MRGPRF interaction in primary melanoma cells needs to be verified." (PMID 40788071, 2025). "The catalytic domain of USP45 is critical for its function as a DUB, as the USP45 C199A mutant loses the ability to stabilize MRGPRF and suppress melanoma." (PMID 40788071, 2025). "It is possible that the promoter of USP45, like that of MRGPRF, is hypermethylated, leading to decreased expression in melanoma." (PMID 40788071, 2025). "Notably, although both USP45 and MRGPRF play critical roles in controlling melanoma development, their functions in melanocytes, the cells from which melanoma originates, remain undetermined." (PMID 40788071, 2025). "Additionally, we investigated the mechanism that governs the interaction between USP45 and MRGPRF in melanoma." (PMID 40788071, 2025). "To investigate whether USPs influence the proteostasis of MRGPRF, thereby regulating melanoma tumorigenesis, we initially screened 40 USPs that may influence the stability of MRGPRF and identified USP45 as a potent stabilizer of MRGPRF." (PMID 40788071, 2025). "Because USP45 is a DUB that removes the ubiquitin chain from its substrates, we tested whether its catalytic domain is required for its anticancer function in melanoma cells." (PMID 40788071, 2025). "Immunohistochemistry on melanoma patient biopsies demonstrates that USP45 expression is markedly reduced in melanoma tissues compared to adjacent noncancerous epidermis." (PMID 40788071, 2025). "Given that both USP45 and MRGPRF repress melanoma and that USP45 stabilizes MRGPRF, we investigated whether MRGPRF acts downstream of USP45 in inhibiting melanoma." (PMID 40788071, 2025). "Next, we examined the expression of USP45 in melanoma tissues and adjacent noncancerous epidermis." (PMID 40788071, 2025). "Supporting this theory, we observed that USP45 affects the stability of MRGPRF protein, indicating that a dysregulated ubiquitin–proteasome system may also contribute to reduced MRGPRF expression and melanoma tumorigenesis." (PMID 40788071, 2025). "In summary, our data demonstrate that USP45 functions as a melanoma suppressor, at least in part, by stabilizing MRGPRF, thereby attenuating the PI3K/AKT pathway, inhibiting proliferation, inducing cell cycle arrest, promoting apoptosis, and mitigating the migration and invasion of melanoma cells." (PMID 40788071, 2025). "Additionally, our finding that USP45 mRNA and protein levels are downregulated in melanoma compared to noncancerous epidermis indicates that USP45 expression may be tightly controlled at multiple levels, such as transcriptional, translational, or posttranslational." (PMID 40788071, 2025). "Whether the antimelanoma effect of USP45 is mediated by MRGPRF in these xenograft tumors, and whether USP45 overexpression represses melanoma metastasis, has not been tested." (PMID 40788071, 2025).
myeloma (1 paper, 2019). "ASB15 is a component of the ubiquitin–proteasome system (UPS) that has been implicated in deficient DNA repair in myeloma by another UPS protein: USP 45 (ubiquitin specific peptidase 45)." (PMID 31139207, 2019). "USP45 is a deubiquitylating enzyme (deubiquitylase) that has been recently linked to myeloma risk in high-risk pedigrees." (PMID 31139207, 2019).
visual disorders (1 paper, 2016). "It is also worth noting that Usp45, Usp53 and Usp54 did show layer specificity, as they were mainly expressed in the photoreceptors (PhR inner segment, ONL and OPL), suggesting a specific role for these genes in photoreceptors and underscoring their role as potential candidates for visual disorders." (PMID 26934049, 2016).
xeroderma pigmentosum (1 paper, 2022). Xeroderma pigmentosum (XP) is a rare genodermatosis characterized by extreme sensitivity to ultraviolet (UV)-induced changes in the skin and eyes, and multiple skin cancers. "Only BRCC3 (p-value log(−10) = 1.87), WRN (p-value log(−10) = 2.09), USP45 (p-value log(−10) = 1.52) and the xeroderma pigmentosum complementation group A (XPA; p-value log(−10) = 1.32) were significantly upregulated." (PMID 36010871, 2022).
cancer (7 papers, 2017 to 2025). A tumor composed of atypical neoplastic, often pleomorphic cells that invade other tissues. "The structural variants, gene mutations and gene copy number alteration of USP45 were analyzed using the TCGA Pan-Cancer Atlas Studies dataset in the cBioPortal database." (PMID 35836933, 2022). "The results of pan-cancer analysis showed that the USP45 gene had a low frequency of structural variants, mainly present in PRAD and LIHC." (PMID 35836933, 2022). "Interestingly, several recent reports have implicated the involvement of USP45 in cancer progression." (PMID 40067150, 2025). "In conclusion, we have demonstrated that USP45 may play a critical role in enhancing cell survival after cancer treatments, and USP45 inhibition causing MYC destabilization may provide a new strategy for clinical CSC treatments." (PMID 36765885, 2023). "In particular, the functional literature supports USP45 as a candidate cancer risk gene." (PMID 29389935, 2018). "The “TIMER2.0” database was utilized for analyzing the USP45 expression level in various cancers, the result showed that the USP45 expression in partial cancer tissues was higher than normal." (PMID 36765885, 2023). "The results from the “GTBAdb” database suggested that high USP45 expressing activated the cancer signaling, including MYC pathways." (PMID 36765885, 2023). "In summary, we demonstrated that USP45 overexpression promoted cancer proliferation, stemness, drug resistance, and transformation of SiHa cells into CSC-like cells." (PMID 36765885, 2023). "In summary, AMG, as the inhibitor of USP45, suppressed cancer development, stemness and drug resistance." (PMID 36765885, 2023). "The results showed that USP45 was positively related to the majority of Writer, Eraser, Reader of m6A RNA methylation, m5C RNA methylation, and m1A RNA methylation in pan-cancer." (PMID 35836933, 2022). "In this study, we firstly explored the putative oncogenic role of USP45 in pan-cancer, including the correlation between USP45 and tumor prognosis, mRNA methylation, tumor heterogeneity, tumor stemness, tumor immunity." (PMID 35836933, 2022). "In this study, we took USP45 as our subject and revealed its important role in the development of different types of tumors through pan-cancer analysis." (PMID 35836933, 2022). "In this study, we comprehensively explored the role of USP45 in different types of tumor through pan-cancer analysis for the first time." (PMID 35836933, 2022). "The pan-cancer analysis showed that USP45 was closely related to mRNA methylation, tumor heterogeneity and tumor stemness." (PMID 35836933, 2022). "The results of pan-cancer analysis showed that the expression of USP45 was negatively correlated with the overall survival (OS) of BRCA, CESC, KIRP, LIHC, and SARC." (PMID 35836933, 2022). "Interestingly, decreased USP45 activity by AMG inhibition significantly suppressed cancer cell proliferation, stemness and drug resistance." (PMID 36765885, 2023). "Through pan-cancer analysis, we found that the mRNA expression levels of USP45 were upregulated in the majority types of tumors, suggesting that USP45 may be involved in tumorigenesis and development as an putative oncogene." (PMID 35836933, 2022). "In conclusion, our study showed that USP45 acted as a novel putative oncogene and might play an important role in the development of pan-cancer." (PMID 35836933, 2022). "Gene Ontology (GO) annotation for molecular function, biological processes and Reactome Pathways indicated that SP100 and USP45 are involved in DNA repair while ZNF534 is involved in DNA-templated regulation of transcription, making them good candidate cancer predisposing genes." (PMID 30947698, 2019). "Further, USP45 overexpressing can upregulate MYC, and this overexpressing can significantly enhance cancer development, cancer cell stemness and drug resistance." (PMID 36765885, 2023).
cancer (continued). "The discovered direct relationship between USP45 and MYC can be used for suppressing MYC and cancer stemness." (PMID 36765885, 2023). "In general, on the basis of our USP45 discoveries on its MYC deubiquitination and α-mangostin inhibition, suppressing USP45 has opened a new window for suppressing cancer development, stemness and drug resistance." (PMID 36765885, 2023). "USP45 complexed with Spindly promotes cancer cell migration, and as a critical regulator in DNA damage repair via deubiquitinating ERCC1 it, in turn, stabilizes the XPF–ERCC1 complex promoting survival of cancer cells exposed to the DNA damage agents in cancer treatments." (PMID 36765885, 2023). "Interestingly, without enhancing cancer development, MYC silencing with shRNA can only suppress USP45-induced stemness and drug resistance." (PMID 36765885, 2023).